SIX5 (SIX homeobox 5)
Description:
Transcription factor that is thought to be involved in regulation of organogenesis. May be involved in determination and maintenance of retina formation. Binds a 5'-GGTGTCAG-3' motif present in the ARE regulatory element of ATP1A1. Binds a 5'-TCA[AG][AG]TTNC-3' motif present in the MEF3 element in the myogenin promoter, and in the IGFBP5 promoter (By similarity). Thought to be regulated by association with Dach and Eya proteins, and seems to be coactivated by EYA1, EYA2 and EYA3 (By similarity).
Synonyms: DMAHP; BOR2
Tractability: PROTAC: ubiquitination databases record sites on it.
Gene: Protein-coding gene on chromosome 19 (45,764,785 to 45,769,252, reverse strand). Ensembl gene ENSG00000177045.
Subcellular location: Cytoplasm; Nucleus
Subcellular location (Human Protein Atlas): Cytosol; Golgi apparatus; Nucleoplasm; Vesicles
Gene Ontology:
Molecular function: protein binding; DNA-binding transcription factor activity, RNA polymerase II-specific; RNA polymerase II cis-regulatory region sequence-specific DNA binding; DNA binding; DNA-binding transcription activator activity, RNA polymerase II-specific; sequence-specific DNA binding
Biological process: regulation of transcription by RNA polymerase II; negative regulation of DNA-templated transcription; negative regulation of skeletal muscle satellite cell proliferation; positive regulation of transcription by RNA polymerase II; regulation of DNA-templated transcription
Cellular component: cytosol; nucleoplasm; chromatin; nucleus; transcription regulator complex; cytoplasm
Genetic constraint (gnomAD): Loss-of-function variants: 19 observed, 25.81 expected, observed/expected ratio (o/e) 0.74, 90% interval 0.51 to 1.08. The synonymous counts are far from expectation, so gnomAD's model fits this gene poorly and the ratio says little. Missense variants: 1,077 observed, 808.55 expected, observed/expected ratio (o/e) 1.33, 90% interval 1.27 to 1.4. Synonymous variants: 595 observed, 400.11 expected, observed/expected ratio (o/e) 1.49, 90% interval 1.39 to 1.59.
Gene-disease validity (ClinGen):
ClinGen rates the evidence that SIX5 causes each of these diseases.
branchio-oto-renal syndrome (autosomal dominant): Disputed.
Homologues: Orthologues: chimpanzee SIX5 (99% identical), macaque SIX5 (98% identical), dog SIX5 (91% identical), guinea pig SIX5 (91% identical), pig SIX5 (91% identical), mouse Six5 (85% identical), rat Six5 (85% identical), zebrafish six5 (33% identical), zebrafish six4b (26% identical), zebrafish six4a (25% identical), Drosophila melanogaster Optix (18% identical), Caenorhabditis elegans ceh-32 (17% identical). Paralogues in human: SIX4 (31% identical), SIX2 (18% identical), SIX1 (17% identical), SIX3 (17% identical), SIX6 (16% identical), ANHX (12% identical).
Diseases named in the same sentence as SIX5 in open-access papers:
SIX5 is named in the same sentence as 42 diseases in open-access papers, as found by Europe PMC text mining. Sharing a sentence is not in itself a finding about the gene and the disease. The quoted sentences say what the papers report.
BOR syndrome (10 papers, 2009 to 2024). "Genetic analysis reveals that mutations in EYA1, SIX1 and SIX5 cause BOR syndrome, an autosomal dominant developmental defect characterised by branchial and external ear malformations, hearing loss and renal anomalies." (PMID 38353121, 2024). "Heterozygous missense variants in the SIX5 (MIM 600963) gene have been reported by one group in patients with BOR syndrome." (PMID 35709191, 2022). "In humans, mutations in EYA1 and its interacting partners SIX1 and SIX5 have been identified as causing BOR syndrome." (PMID 19389353, 2009). "The heterozygous variants of SIX1, EYA1, and SIX5 genes are responsible for BOR syndrome." (PMID 35709191, 2022). "Furthermore, the association of the SIX5 mutation with BOR syndrome has been recently disputed, as Six−/− mice were found to develop only cataract." (PMID 30086703, 2018). "Mutations in EYA1, SIX1 and SIX5 genes have been associated with BOR syndrome." (PMID 23840632, 2013). "Approximately 40% of patients with BOR syndrome carry a pathogenic mutation in EYA1, whereas 9-10% have mutations in SIX1 or SIX5." (PMID 38353121, 2024). "One family has a previously reported SIX5 variant (ENST00000317578.6:c.472G>A, p.Ala158Thr), consistent with Branchiootorenal syndrome 2 (BOR2)." (PMID 36910591, 2023). "These are responsible for about 40% of clinical BOR syndrome, whereas approximately 4 and 5% of patients have pathogenic variants respectively in SIX1 gene and SIX5 gene." (PMID 36183088, 2022). "Recently, mutations in another SIX family member, SIX5 (MIM 610896), have been reported in patients with BOR syndrome." (PMID 23506628, 2013). "BOR syndrome caused by EYA1, SIX1 and SIX5 mutations leads to kidney and urinary tract malformations and hearing impairment." (PMID 19389353, 2009). "In addition, variants in SIX homeobox 1 gene (SIX1 MIM#601205) and SIX homeobox 5 gene (SIX5 MIM#600963) were found to be related to BOR syndrome." (PMID 30548429, 2019). "Indeed, mutations in Six gene family members such as SIX1 and SIX5 also cause BOR syndrome while mutations in SIX2 have been reported in patients with renal hypodysplasia, a phenotype observed in patients with BOR syndrome." (PMID 24489909, 2014). "Interestingly, SIX1, SIX5, and EYA1 are associated with BOR syndrome." (PMID 30086703, 2018). "However, the association of SIX5 mutations with BOR syndrome has not been confirmed by other groups and the pathogenetic role of some SIX5 mutations was reconsider." (PMID 23506628, 2013). "The presence of branchial cysts, cervical fistulae, external ear anomalies and mild renal pyelectasis suggested the clinical diagnosis of BOR syndrome and the analyses of EYA1, SIX1, and SIX5 genes were performed by next generation sequencing (NGS)." (PMID 36183088, 2022).
breast carcinoma (4 papers, 2015 to 2019). "Two of the unique EμMyc/Casp2−/− genes have associated roles in transcription regulation (Six5) and calmodulin binding (Nrgn) and have been previously associated with lung squamous cell carcinoma, breast cancer (Six531,32), and T-cell lymphoma (Nrgn33)." (PMID 30670683, 2019). "Sineoculis homeobox homolog (SIX) family proteins, including SIX1, SIX2, SIX3, SIX4, SIX5, and SIX6, have been implicated in the initiation and progression of breast cancer, but the role of each member in breast tumor is not fully understood." (PMID 27399099, 2016).
cataract (3 papers, 2022 to 2024). Partial or complete opacity of the crystalline lens of one or both eyes that decreases visual acuity and eventually results in blindness. "SIX5 dysfunction is associated with the development of adult-onset cataracts, the most common ocular phenotype in DM." (PMID 35709191, 2022). "Haploinsufficiency of the SIX5 gene induces cataracts with incomplete penetrance as well as mild cardiac conduction defects." (PMID 35408837, 2022). "In DM1, downregulation of these genes by epigenetic changes, such as hypermethylation may participate in some clinical features including cataracts, muscle defects or cardiac conduction abnormalities as observed in DMPK, SIX5 or DMWD knockdown mouse models." (PMID 35408837, 2022). "Although decreased gene expression at the DM1 locus is not sufficient to explain the complex DM1 phenotype, downregulation of DMPK, SIX5 and DMWD genes by epigenic changes in DM1 could participate in some clinical features such as DM1 cataracts, muscle defects or cardiac conduction defects." (PMID 35408837, 2022).
myotonic dystrophy (3 papers, 2010 to 2022). An inherited progressive disorder affecting the muscles. "It has been acknowledged that SIX5 was correlated with eye development and myotonic dystrophy, which are related to embryonic and organismal development." (PMID 32967723, 2020). "DMAHP (SIX5) participates in the pathophysiology of myotonic dystrophy (DM)." (PMID 35709191, 2022).
hyperandrogenism (2 papers, 2022). Excessive secretion of androgens from the adrenal glands or gonads. "For example, gene ontology and pathway analysis showed that dysregulated lncRNAs in GCs in PCOS with hyperandrogenism have a regulatory role in mitochondrial function by interacting with transcription factors such as yin-yang 1 (YY1) and SIX homeobox 5 (SIX5)." (PMID 36498989, 2022). "‐In ovarian granulosa cells from women with PCOS with or without hyperandrogenism‐dysregulated lncRNA in PCOS have a regulatory role in mitochondrial function via interacting with transcription factors such as YY1 and SIX5." (PMID 34989136, 2022).
Obesity (2 papers, 2015 to 2018). Accumulation of substantial excess body fat. "Instead, our screen suggests that different nearby cis gene may be more fruitful for further functional follow up for obesity, namely ZCCHC8, VPS33A, RSRC2; SPDEF, NUDT3; SETD1, VKORC1; SGSM2, SRR; VASP, SIX5; OTX1; BANK1; ARIH1; ELL; CHST8, respectively." (PMID 29608557, 2018).
3MC syndrome (1 paper, 2020). "Several neural crest regulatory molecules are known to cause ear/kidney syndromes with variable expression of both ear and kidney phenotypes (e.g., EYA1, SIX1, SIX5, CHD7, MASP1, TBX1), involved in BOR/BO syndrome, CHARGE syndrome, 3MC syndrome and DiGeorge syndrome." (PMID 32585897, 2020).
Anxiety (1 paper, 2010). Intense feelings of nervousness, tension, or panic often arise in response to interpersonal stresses. "To investigate the contribution of these genes to cognitive symptoms observed in DM1 patients, we studied the effect of deletion of Six5, Dmpk and Mbnl1 on three separate behavioral tasks designed to test learning and memory, anxiety and motivation." (PMID 20360842, 2010). "Although Dmpk−/− and Six5−/− showed no overt anxiety phenotype in the open field, we performed only one test of anxiety and thus subtle phenotypes may exist that can be detected using other tests." (PMID 20360842, 2010).
borderline epithelial ovarian tumors (1 paper, 2022). "For example, SIX5 is potentially a molecular trigger of pathogenesis in borderline epithelial ovarian tumors." (PMID 35387981, 2022).
conduction disorders (1 paper, 2016). "In contrast, our previous studies have shown that deficits of Dmpk and Six5 result in conduction disorders but not echocardiographic abnormalities." (PMID 27484195, 2016).
Fusarium infection (1 paper, 2022). "Taken together, while the expression of SIX5 alone did not affect the disease susceptibility of Arabidopsis toward Fo5176, it did increase disease susceptibility during the early stages of Fusarium infection in the presence of Avr2." (PMID 35968143, 2022).
glioblastoma (1 paper, 2026). The most malignant astrocytic tumor (WHO grade IV). "The SIX transcription factor family has been implicated in tumor development, but the role and regulatory mechanism of SIX5 in glioblastoma (GBM) remain unclear." (PMID 41939887, 2026).
multiple myeloma (1 paper, 2024). "Finally, our analysis unveiled an upregulation of SIX5 expression in multiple myeloma (MM), a PC-derived neoplasm, at both the gene and protein levels." (PMID 38301653, 2024).
nuclear cataract (1 paper, 2016). A cataract (disease) that involves the lens nucleus. "The contribution of Six5 deficits to the development of DM1 ocular defects is unclear, because in mice Six5 loss results in nuclear cataracts, which are not prominent in DM1 patients." (PMID 27484195, 2016).
omphalocele (1 paper, 2018). Omphalocele is an embryopathy classified in the group of abdominal celosomias and is characterized by a large hernia of the abdominal wall, centered on the umbilical cord, in which the protruding viscera are protected by a sac. "Therefore, we emphasize that Six4−/−;Six5−/− mice are a suitable animal model for large and small middle-type omphalocele reproducing typical human omphalocele." (PMID 30237319, 2018). "From the results, we propose that the regulation of cell proliferation and morphological change in the PAW at an early stage is a basis for omphalocele phenotype, and that Six4−/−;Six5−/− mice are a suitable animal model for reproducing human middle-type omphalocele." (PMID 30237319, 2018). "In the present study, we found that Six4−/−;Six5−/− mice show severe ventral body wall closure defects with few other anomalies, they have defects in PAW formation, and that omphalocele formation is in complete penetrance." (PMID 30237319, 2018). "We compared ventral body wall formation in Six4−/−;Six5−/− fetuses with large omphalocele and Six5−/− or Six4+/−;Six5+/− fetuses, which have no apparent defects in ventral body wall closure, at E15.5 and E18.5." (PMID 30237319, 2018). "As morphological differences in the PAW of other mutant mice that exhibit middle-type omphalocele have not been reported, analyses of Six4−/−;Six5−/− mice first revealed that the impaired morphogenesis of the PAW may lead to middle-type omphalocele." (PMID 30237319, 2018). "Although all Six5−/− fetuses had no phenotypic changes in the ventral body (I′), a small number of Six4+/−;Six5−/− fetuses showed an enlarged umbilical ring or a small-type omphalocele (J′)." (PMID 30237319, 2018).
Ventricular hypertrophy (1 paper, 2008). Enlargement of the cardiac ventricular muscle tissue with increase in the width of the wall of the ventricle and loss of elasticity. "Structure-function analysis of Six5+/− cardiac muscle demonstrates that reduced Six5 levels result in mild infra-Hisian conduction delay, increased left ventricular end diastolic dimension, and ventricular hypertrophy." (PMID 19092997, 2008).
cancer (6 papers, 2016 to 2024). A tumor composed of atypical neoplastic, often pleomorphic cells that invade other tissues. "In TP astrocyte, OPC and NFO, the notable TF, BCL11A, is involved in microRNAs in cancer, whereas the TF SIX5 is seen to regulate highest number of processes such as regulation of GTPase activity, cell growth, complement activation, lectin pathway etc." (PMID 34976314, 2022). "Recently, SIX5 has also been identified to play a key role in cancers." (PMID 35387981, 2022). "Cytoband Chr19q13 is the human syntenic segment for chr7 in mice and contains both cancer-related and muscle disease-related genes (DMPK, DMWD, SIX5 related to Myotonic Dystrophy Type 1)." (PMID 38341433, 2024). "Each member of this complex has a specific function: SIX5 can bind to target genes’ promoters, p300 acetylates histones to relax the chromatin structure, and EYA3 acts as a SIX5 coactivator for MMPs’ transcription, inducing cancer progression." (PMID 38069210, 2023). "In one report, SIX5 was detected in normal ovarian epithelium, as well as in malignant ovarian and borderline tumors suggesting that SIX5 could be used as a marker for epithelial differentiation in ovarian tissue rather than a specific marker for cancer." (PMID 34490256, 2021).
infection (6 papers, 2015 to 2022). The state of being infected such as from the introduction of a foreign agent such as serum, vaccine, antigenic substance or organism. "The Avr2-dependent increase in susceptibility to Fusarium in ΔspSIX5 Arabidopsis lines implies a role of Six5 during early infection stages." (PMID 35968143, 2022). "The effectors Avr2 and Six5 secreted by F. oxysporum interact at the PD during its infection of tomato; however, Avr2 only moves cell-to-cell in the presence of Six5, while Six5 alone does not alter plasmodesmal conductivity." (PMID 34149749, 2021). "We hypothesize that the endogenous function of Six5 is to aid the spread of Avr2 in root tissues surrounding the infection zone, allowing the effector to suppress PTI ahead of the fungus, thereby contributing to infection." (PMID 35968143, 2022).
tumor (6 papers, 2016 to 2026). "Single-cell RNA sequencing and spatial transcriptomics showed enrichment of SIX5 in the tumor core and in astrocyte-like and stem cell-like subsets at the invasion front." (PMID 41939887, 2026). "In a recent study, SIX5 was shown to correlate with clinic-pathological parameters, e.g. tumour stage, size etc., of BC patients." (PMID 27876826, 2016). "Our meta-analysis indicated that the SIX5 was involved in tumor formation of NSCLC." (PMID 27821176, 2016). "In conclusion, SIX5 functions as a critical oncogenic driver in GBM, regulated by KDM5C and promoting tumor progression through UBE2C-mediated activation of AKT/mTOR signaling and glycolytic reprogramming." (PMID 41939887, 2026). "Continuing with hypermethylated DMRs overlapping homeobox genes in a single tumor tissue that also meets our set threshold, the KIRP, or kidney renal papillary cell carcinoma, dataset yielded SIX5 as a potential biomarker." (PMID 38886487, 2024). "SIX5 is participated in both ceRNA networks of LINC01842 and VPS9D1-AS1 and reported to overexpressed in NSCLC tissues and correlated with the tumor grade." (PMID 31720124, 2019).
SIX5 also shares sentences with these, for which no sentence is quoted: Hearing impairment (3 papers); myotonic dystrophy type 1 (2); Adult onset (1); branchio-oto-renal syndrome (1); branchiootic syndrome 1 (1); CHARGE syndrome (1); congenital hypopituitarism (1); deafness (1); DiGeorge syndrome (1); Epstein syndromes (1); genetic disorders (1); Heart block (1); Insulin resistance (1); kidney failure (1); liver steatosis (1); lung adenocarcinoma (1); lung squamous cell carcinoma (1); microtia (1); renal agenesis (1); renal dysplasia (1); Sensorineural hearing impairment (1); T-cell lymphoma (1); Waardenburg syndrome (1).